ZNF658 (zinc finger protein 658)
Description:
Mediates transcriptional repression in response to zinc. Represses several genes, including SLC30A5, SLC30A10 and CBWD1, by binding to the zinc transcriptional regulatory element (ZTRE) (5'-C[AC]C[TAG]CC[TC]-N(0-50)-[GA]G[ATC]G[TG]G-3') found in the promoter region. May play a role in the control of ribosome biogenesis, regulating predominantly rRNA levels, as well as those of several ribosomal proteins, thus coordinating this highly zinc-demanding process with the available zinc supply.
Synonyms: MGC35232; DKFZp572C163; FLJ32813
Tractability: PROTAC: UniProt records ubiquitination sites on it; ubiquitination databases record sites on it.
Gene: Protein-coding gene on chromosome 9 (66,856,426 to 66,932,141, forward strand). Ensembl gene ENSG00000274349.
Subcellular location: Nucleus
Subcellular location (Human Protein Atlas): Nucleoplasm
Pathways (Reactome):
Gene expression (Transcription): Generic Transcription Pathway
Gene Ontology:
Molecular function: transcription cis-regulatory region binding; sequence-specific double-stranded DNA binding
Biological process: cellular response to zinc ion; negative regulation of DNA-templated transcription; ribosome biogenesis; negative regulation of transcription by RNA polymerase II; regulation of DNA-templated transcription
Cellular component: nucleus
Genetic constraint (gnomAD): Loss-of-function variants: 43 observed, 58.5 expected, observed/expected ratio (o/e) 0.74, 90% interval 0.57 to 0.95. The upper end of that interval is the gene's LOEUF score, 0.95, which puts it in group 4 of 6, group 1 being the genes least tolerant of losing a copy. Missense variants: 666 observed, 847.01 expected, observed/expected ratio (o/e) 0.79, 90% interval 0.74 to 0.84. Synonymous variants: 247 observed, 283.91 expected, observed/expected ratio (o/e) 0.87, 90% interval 0.78 to 0.97.
Homologues: Orthologues: chimpanzee ZNF658 (99% identical), macaque ZNF658 (95% identical), pig ZNF658 (63% identical). Paralogues in human: ZNF33B (34% identical), ZNF484 (33% identical), ZNF585B (32% identical), ZNF717 (31% identical), ZNF41 (31% identical), ZNF585A (30% identical), ZNF470 (30% identical), ZNF28 (30% identical), ZNF334 (30% identical), ZNF197 (30% identical), ZNF605 (30% identical), ZNF12 (29% identical), and 164 more.
Diseases named in the same sentence as ZNF658 in open-access papers:
ZNF658 is named in the same sentence as 2 diseases in open-access papers, as found by Europe PMC text mining. Sharing a sentence is not in itself a finding about the gene and the disease. The quoted sentences say what the papers report.
breast carcinoma (1 paper, 2022). "However, further in vitro experiments, which were beyond the scope of the present translational study, will be needed in order to confirm the putative role of GLIS3 and ZNF658 in FNTB’s transcriptional regulation and its effects on oncogenic RAS signalling in breast cancer." (PMID 35158735, 2022).
lymph node (1 paper, 2024). "In contrast, amplification of ZNF658 on 9q12, a potential driver SCNA, was detected in both rNEN-S and lymph node metastatic rNEN-L subjects." (PMID 39548061, 2024).